SIRT1 (sirtuin 1)
Diseases named in the same sentence as SIRT1 in open-access papers (continued):
Sharing a sentence is not in itself a finding about the gene and the disease.
bone cyst (3 papers, 2020 to 2021). "In this report we used 3 dimensional (3D) alginate hydrogel combined with SIRT1+ ASCs for subchondral bone cyst treatment in medial femoral condyle in the horse." (PMID 32803696, 2020). "Here, we combined SIRT1+ MSCs with alginate hydrogel for subchondral bone cyst treatment in medial femoral condyle in the horse." (PMID 32803696, 2020). "Interestingly, SIRT1 and NAD+ co-factor deficiency is prominent in OA patients and experimental models of skeletal diseases." (PMID 34833421, 2021). "Finally, application of SIRT1 + ASCs combined with 3D hydrogel for subchondral bone cysts treatment replace it with normal bone tissue and allows to full recovery from the disease." (PMID 32803696, 2020). "We believe, that the combination of SIRT1 + stem cells and 3D biodegradable matrix might become an effective strategy for subchondral bone cyst treatment." (PMID 32803696, 2020).
central nervous system diseases (3 papers, 2021 to 2025). "Previous studies have demonstrated that SIRT1 plays a key role in different central nervous system diseases." (PMID 33830639, 2021). "SIRT1 is activated in many central nervous system diseases, such as subarachnoid haemorrhage and Parkinson's disease." (PMID 33830639, 2021). "Due to its exceptional performance in the body’s defense mechanisms and death modes such as oxidative stress, inflammation, apoptosis, and ferroptosis, the role of SIRT1 in the pathological process of central nervous system disease and injury is worth inferring." (PMID 38671843, 2024). "Furthermore, Sirtuin 1 (SIRT1), a conserved sirtuin, regulates various cellular processes and exerts neuroprotective effects in diverse central nervous system disorders, primarily by activating the PGC-1α/NRF2 signaling pathways." (PMID 41359280, 2025).
musculoskeletal disorders (3 papers, 2024 to 2025). "Specifically, in the musculoskeletal disorders group, the SIRT1 concentration in the case group was 1.72 ng/mL higher than in the control group (WMD, 1.72 ng/mL; 95% CI 1.37, 2.06 ng/mL; P< 0.001; I2 = 95.1%)." (PMID 39676853, 2024). "Additionally, the disease category subgroup analysis showed a significant positive correlation between inflammation and SIRT1 levels in subjects suffering from musculoskeletal disorders." (PMID 39676853, 2024).
myopathies (3 papers, 2016 to 2025). "In the current study, our results indicated that LLL irradiation restores down-regulated SIRT1 and PGG-1α expression, suggesting that SIRT1/PGC-1α forms a regulatory axis to control mitochondrial function in Dox-induced myopathy." (PMID 34876217, 2021).
neurodevelopmental disorder (3 papers, 2022 to 2023). A behavioral and cognitive disorder with onset during the developmental period that involves impaired or aberrant development of intellectual, motor, or social functions. "Notably, Ube3a and Sirt1 are known to play a role in chromatin remodeling and neurodevelopmental disorders." (PMID 35466187, 2022).
vasculopathy (3 papers, 2023 to 2025). "SIRT1 could reduce retinal damage and vasculopathy by inhibiting inflammatory responses and attenuating oxidative stress and apoptosis." (PMID 38633216, 2024).
Endocrine Disorders (2 papers, 2022 to 2023). "This leads to several unanswered questions about the underlying molecular mechanism on SIRT1-autophagy-endocrine disorder axis." (PMID 35909524, 2022). "However, most studies have only demonstrated the association between SIRT1-mediated autophagy and endocrine disorders." (PMID 35909524, 2022). "Although the mechanism underlying the effect of resveratrol on endocrine disorder in humans remain unclear, in vivo studies describe that resveratrol may target the SIRT1-autophagy axis to improved disease condition." (PMID 35909524, 2022). "Dysregulation in SIRT1-mediated autophagy hinders the proper functioning of the endocrine system, contributing to the onset and progression of endocrine disorders." (PMID 35909524, 2022). "Given that SIRT1 can regulate different steps of autophagy process, it still remains unclear through which mechanism SIRT1 regulate autophagy to induce endocrine disorder." (PMID 35909524, 2022). "In addition to resveratrol, recently several studies have reported the beneficial effect of NAD+ supplements in preventing endocrine disorders by increasing SIRT1 levels and activity." (PMID 35909524, 2022). "Therefore, the clinical and in vivo findings overall suggest resveratrol as a potential therapy which targets SIRT1-mediated autophagic pathway to treat endocrine disorders." (PMID 35909524, 2022). "Moreover, the SIRT1-autophagy-endocrine disorder interplay indicates that SIRT1-mediated autophagy may play a key role in the onset and progression of endocrine disorders." (PMID 35909524, 2022).
gastrointestinal disease (1 paper, 2024). A disease that occurs in the gastrointestinal system, excluding the hepatobiliary system. "Previous studies have linked SIRT1 to the regulation of autophagy in gastrointestinal diseases, where its role in maintaining cellular homeostasis is critical." (PMID 39494277, 2024).
hematologic cancers (1 paper, 2022). "The impact of SIRT1 expression in other on hematologic cancers is controversial." (PMID 36600891, 2022).
intestinal diseases (1 paper, 2022). "In addition, both protective and deleterious effects of SIRT1 have been explored in intestinal diseases." (PMID 36581622, 2022). "The proinflammatory effects of SIRT1 and regulation of different immune cells might play an important role in aggravating intestinal diseases." (PMID 36581622, 2022).
neuromuscular disease (1 paper, 2018). "SIRT1 has been shown to influence stress resistance, mitochondrial oxidative phosphorylation, and autophagy, suggesting that this protein could also impact NMJ degeneration during normal aging and neuromuscular disease." (PMID 30295421, 2018).
SIRT1 also shares sentences with these, for which no sentence is quoted: Parkinson’s (15 papers); acute myocardial infarction (11); hypertrophy (7); ischemia reperfusion injury (7); motor neuron diseases (7); alcohol (6); cognitive disorder (5); neurotoxicity (5); pancreatic adenocarcinoma (5); chronic periodontitis (4); clear cell renal cell carcinoma (4); left ventricular hypertrophy (4); actinic keratosis (3); chronic heart failure (3); colorectal adenocarcinoma (3); hemorrhage (3); hypopharyngeal carcinoma (3); knee osteoarthritis (3); liver dysfunction (3); Pain (3); pancreatitis (3); Premature ovarian insufficiency (3); prostate (3); serous ovarian cancer (3); acute liver failure (2); Allergy (2); arteriosclerosis (2); autistic spectrum disorder (2); benign prostatic hyperplasia (2); bone cancer (2).
A further 181 diseases each share a sentence with SIRT1 in 2 papers or fewer.